MCU (mitochondrial calcium uniporter)
Description:
Channel-forming and calcium-conducting subunit of the mitochondrial inner membrane calcium uniporter complex (uniplex), which mediates calcium uptake into the mitochondrial matrix. MCU channel activity is regulated by the calcium-sensor subunits of the uniplex MICU1 and MICU2 (or MICU3). Mitochondrial calcium homeostasis plays key roles in cellular physiology and regulates ATP production, cytoplasmic calcium signals and activation of cell death pathways. Involved in buffering the amplitude of systolic calcium rises in cardiomyocytes. While dispensable for baseline homeostatic cardiac function, acts as a key regulator of short-term mitochondrial calcium loading underlying a 'fight-or-flight' response during acute stress: acts by mediating a rapid increase of mitochondrial calcium in pacemaker cells. Participates in mitochondrial permeability transition during ischemia-reperfusion injury (By similarity). Mitochondrial calcium uptake in skeletal muscle cells is involved in muscle size in adults (By similarity). Regulates synaptic vesicle endocytosis kinetics in central nerve terminal (By similarity). Regulates glucose-dependent insulin secretion in pancreatic beta-cells by regulating mitochondrial calcium uptake. Involved in antigen processing and presentation (By similarity).
Synonyms: HsMCU; C10orf42; CCDC109A; FLJ46135
Tractability: Small molecule: a structure with a bound ligand is known. Antibody: UniProt predicts a signal peptide or a membrane-spanning region. PROTAC: ubiquitination databases record sites on it; its protein half-life has been measured.
Gene: Protein-coding gene on chromosome 10 (72,692,110 to 72,887,694, forward strand). Ensembl gene ENSG00000156026.
Subcellular location: Mitochondrion inner membrane
Subcellular location (Human Protein Atlas): Mitochondria
Pathways (Reactome):
Transport of small molecules: Mitochondrial calcium ion transport; Processing of SMDT1
Gene Ontology:
Molecular function: calcium channel activity; protein binding; uniporter activity
Biological process: calcium import into the mitochondrion; calcium-mediated signaling; cellular response to calcium ion starvation; glucose homeostasis; mitochondrial calcium ion homeostasis; mitochondrial calcium ion transmembrane transport; positive regulation of insulin secretion; positive regulation of mitochondrial calcium ion concentration; positive regulation of mitochondrial fission; positive regulation of neutrophil chemotaxis; protein complex oligomerization; positive regulation of apoptotic process
Cellular component: calcium channel complex; mitochondrial inner membrane; mitochondrion; uniplex complex
Genetic constraint (gnomAD): Loss-of-function variants: 7 observed, 29.91 expected, observed/expected ratio (o/e) 0.23, 90% interval 0.13 to 0.44. The upper end of that interval is the gene's LOEUF score, 0.44, which puts it in group 1 of 6, group 1 being the genes least tolerant of losing a copy. Missense variants: 262 observed, 348.21 expected, observed/expected ratio (o/e) 0.75, 90% interval 0.68 to 0.83. Synonymous variants: 143 observed, 135.08 expected, observed/expected ratio (o/e) 1.06, 90% interval 0.92 to 1.22.
Homologues: Orthologues: chimpanzee MCU (100% identical), macaque MCU (99% identical), dog MCU (99% identical), rabbit MCU (98% identical), guinea pig MCU (96% identical), mouse Mcu (96% identical), rat Mcu (89% identical), pig MCU (86% identical), tropical clawed frog mcu (76% identical), zebrafish mcu (70% identical), Drosophila melanogaster MCU (42% identical), Caenorhabditis elegans mcu-1 (36% identical). Paralogues in human: MCUB (42% identical).
Diseases named in the same sentence as MCU in open-access papers:
MCU is named in the same sentence as 115 diseases in open-access papers, as found by Europe PMC text mining. Sharing a sentence is not in itself a finding about the gene and the disease. The quoted sentences say what the papers report.
breast carcinoma (35 papers, 2014 to 2025). "The analysis further revealed that MCU, alongside genes commonly mutated in breast cancer, demonstrated elevated expression levels comparable to key T cell regulators such as AHR, ID2, and TBFb1." (PMID 38632642, 2024). "MCU overexpression appears to be intricately linked to immune infiltration within the tumor microenvironment of Breast Cancer (BRCA), exhibiting a significant positive correlation with T cell CD8 + (rho = 0.344, p < 0.001)." (PMID 38632642, 2024). "While this article delves into the mutation of MCU in breast cancer, it's crucial to note that MCUb forms hetero-oligomers with MCU, and expressing MCUB alone in the lipid bilayer hardly facilitates Ca2 + exchange across the artificial membrane." (PMID 38632642, 2024). "Previous study reported that MCU overexpression is in association with poor prognosis of breast cancer." (PMID 32152662, 2020). "Recently, clinical data analysis of breast cancer patients has associated overexpression of MCU and downregulation of MICU1 to poor prognosis suggesting that mitochondrial Ca2+ uptake accelerates cancer dissemination." (PMID 28495532, 2018). "From these gain- and loss-of-function assays, we concluded that MCU promotes migration and invasion of breast cancer cells by regulating [Ca2+]m uptake." (PMID 29137386, 2017). "Interestingly, two independent studies, in MDA-MB-231 and Hs578t breast cancer cell lines have associated MCU loss to a SOCE defect where MCU silencing considerably reduced cytosolic Ca2+ entry after ER-store depletion upon thapsigargin treatment." (PMID 28495532, 2018). "Similarly, we demonstrated that MCU expression is positively associated with metastasis in human breast cancer cell lines." (PMID 29137386, 2017). "Because MCU is a key ion channel protein in the mitochondria, we assessed whether gain- and loss-of-function of MCU affects glycolysis in breast cancer cells." (PMID 29137386, 2017). "Recently, MCU expression was linked to redox status in breast cancer cell lines." (PMID 27827394, 2016). "Furthermore, MCU deficiency decelerated the invasion of breast cancer cells." (PMID 38632642, 2024). "Remarkably, MCU is highly expressed in various cancer cells including breast cancer cells, thereby increasing the capacity of mitochondrial Ca2+ uptake, ATP production, and cell proliferation." (PMID 39866241, 2025). "MCU is highly expressed in various cancer cells including breast cancer cells, thereby increasing the capacity of mitochondrial Ca2+ uptake, ATP production, and cancer cell proliferation." (PMID 39866241, 2025). "The interplay of calcium balance through MCU and the sodium-calcium exchanger is known, but its regulation in the breast cancer tumor microenvironment remains elusive." (PMID 38632642, 2024). "Consistently, MCU expression is elevated in various types of cancer, including breast cancer, hepatocellular carcinoma, melanoma, and CRC." (PMID 39466877, 2024). "MCU overexpression is also correlated with poor patient prognosis and with lymph node invasion in breast cancer patients." (PMID 38538285, 2024). "Across various breast cancer subtypes, MCU expression was consistently lower in normal tissue compared to other subtypes." (PMID 38632642, 2024). "Overall, MCU plays a critical role as checkpoint of the metastatic behavior in breast cancer, thus enlightening its potential role as pharmacological target in this aggressive type of cancer." (PMID 37759703, 2023). "Genetic silencing of MCU in the breast cancer cell line MDA-MB-231 reduced cell motility and invasiveness in vitro, as well as tumor growth, lymph node infiltration and lung metastasis in vivo." (PMID 37363724, 2023). "Previous studies have suggested a role for MCU as a promoter of invasion and metastasis in breast cancer and colorectal carcinoma-derived cell lines." (PMID 37363724, 2023). "For instance, MCU overexpression in breast cancer correlates with tumour size, invasiveness and poor prognosis." (PMID 35490194, 2022).
breast carcinoma (continued). "In HCC as well as in breast cancer, MCU overexpression results in increased Ca2+ uptake and mROS generation, which play an important role in driving tumour progression and metastasis." (PMID 35490194, 2022). "Mitochondrial calcium uniporter (MCU) is the selective channel responsible for mitochondrial Ca2+ uptake leading to mtROS generation and HIF1α signaling events for breast cancer progression." (PMID 36154922, 2022). "Depletion of mitochondrial calcium uniporter (MCU) decreases cell migration in various breast cancer cells." (PMID 35186947, 2021). "The glycolytic process increases the mitochondrial Ca2+ through mitochondrial calcium uniporter (MCU), thus overexpressed MCU channels are widely found in breast carcinoma patients." (PMID 34717757, 2021). "Several studies have shown that MCU plays a pivotal role in breast cancer progression and metastasis and that it is a candidate therapeutic target and biomarker for breast cancer." (PMID 33430230, 2021). "This also correlates with observations that MCU expression is further elevated in metastatic disease in many breast cancer subtypes." (PMID 32059571, 2020). "Accordingly, reduced MICU1 levels and high MCU:MICU1 ratios have been associated with poor disease outcomes in patients with hepatocellular carcinoma and breast cancer, respectively." (PMID 33114428, 2020). "Upon MCU knockdown, migration and invasion of breast cancer cells were decreased, and in vivo tumor growth abrogated." (PMID 32059571, 2020). "MCU expression was reported to correlate with metastasis and invasiveness of breast cancer also in another work, likely due to its ability to regulate store-operated Ca2+ entry (SOCE), that is known to be involved in migration." (PMID 31159324, 2019). "In support, silencing of the MCU gene in human breast cancer and HeLa cells leads to an increase in actin cytoskeleton stiffness, loss of cell polarity, as well as impairment of focal adhesion dynamics." (PMID 30255402, 2018). "We identified a novel mechanism that upregulated MCU promotes breast cancer metastasis via enhancing glycolysis, and that this process is posttranscriptionally and negatively regulated by microRNA-340." (PMID 29137386, 2017). "In the present study, we provide the first evidence that upregulated MCU expression enhances the metastatic capacity of breast cancer cells by inducing a shift from oxidative to glycolytic metabolism." (PMID 29137386, 2017). "The in vivo growth of breast cancer cells in which MCU was deleted was severely impaired, correlating with an altered cellular redox state and impaired mitochondrial production of ATP." (PMID 28516062, 2017). "It was shown that MCU expression positively correlated with the metastatic phenotype and clinical stage of the breast cancers, while the expression of MCUb, a negative regulator of MCU, displayed a negative correlation." (PMID 28516062, 2017). "MCU overexpression promoted motility and enhanced the Warburg effect in breast cancer cells, and miR-340 directly targeted MCU mRNA to suppress MCU expression in these cells." (PMID 29137386, 2017). "We further demonstrate that miR-340 directly targets and downregulates MCU expression to suppress glycolysis and motility in breast cancer cells." (PMID 29137386, 2017). "Our results elucidate a novel mechanism, the miR-340/MCU pathway, is involved in breast cancer metastasis." (PMID 29137386, 2017). "Taken together, findings from our studies and others provide new evidence of MCU involvement in driving metastatic progression in breast cancer." (PMID 29137386, 2017). "We evaluated MCU overexpression or knock-down on migration, invasion and glucose metabolismin breast cancer cells." (PMID 29137386, 2017). "Serum-induced migrations in these MDA-MB-231 cells were blocked by SOCE inhibitors, suggesting that MCU plays a critical role in breast cancer cell migration by regulating SOCE." (PMID 27289382, 2016).
breast carcinoma (continued). "Interestingly, a majority of the studies that have investigated the role of MCU in breast cancer migration and invasion have used TNBC cell lines to address these questions due to the aggressive nature of this cancer." (PMID 38538285, 2024). "In breast cancer samples, MCU expression positively correlates with tumor progression, suggesting that mitochondrial Ca2+ uptake could be advantageous for cancer growth and metastasis." (PMID 36994106, 2023). "Thus, MCU was overrepresented in more aggressive and metastatic breast cancers, and downregulation of MCU in metastatic cell lines resulted in impaired growth, migration, and invasion in vitro, and metastasis and lymph node infiltration in vivo." (PMID 34069047, 2021). "In another work, it has been proposed that a small molecule, AG311, shown to retard tumor growth and to reduce lung metastases, might induce breast cancer cell death by activating MCU, although direct proof is missing." (PMID 31159324, 2019). "Moreover, MCU overexpression was also found to be necessary for breast carcinoma migration and progression, by increasing tumor size and lymph node infiltration." (PMID 30011966, 2018). "In addition, MCU silencing has been proved to sensitize breast cancer cells to caspase-independent vs caspase dependent cell death." (PMID 30011966, 2018). "MCU silencing using siRNA or inhibition by ruthenium red has been reported to result in impairment of SOCE as well as migration in triple negative MDA-MB-231 breast cancer cells." (PMID 30558192, 2018). "Finally, the fact that MCU is overexpressed in breast cancer patients and the clear evidence linking MCU to cancer invasion and growth, points to mitochondrial Ca2+ uptake as a potential therapeutic target in highly proliferative cancers." (PMID 28495532, 2018). "Moreover, a novel mechanism was identified that MCU was a direct target of microRNA-340, which suppressed breast cancer cell motility by inhibiting glycolysis." (PMID 29137386, 2017). "To confirm that MCU, a major Ca2+ channel in the inner mitochondrial membrane, is involved in breast cancer cell migration and invasion, we measured MCU expression in four breast cancer cell lines with different metastatic potential (BT-474, MCF7, ZR-75-30, and MDA-MB-231)." (PMID 29137386, 2017). "Furthermore, MCU expression correlates with mammary tumor size and lymph node infiltration in mice and is an indicator of poor prognosis for breast cancer." (PMID 29137386, 2017). "Finally, the role of MCU in the control of breast cancer cell migration has been ascribed to a store‐operated Ca2+ entry‐dependent mechanism." (PMID 27138568, 2016). "However, a recent study reported a correlation between MCU overexpression and poor prognosis in breast cancer patients." (PMID 27138568, 2016). "Finally, in breast cancer mRNA samples, a positive correlation of MCU expression with HIF‐1α signaling route is present." (PMID 27138568, 2016). "A significantly poorer prognosis was associated with MCU over expression and MICU1 under expression suggesting the expression of Ca2+ uniporter subunits may play an important role in breast cancer biology." (PMID 24802861, 2014). "Indeed, MCU complex has been shown to be also related to breast cancer." (PMID 30011966, 2018). "Similarly, in breast cancer, the downregulation of miR-340 is correlated with increased MCU expression in highly metastatic cells, while MCU targeting by miR-340 blocks the metabolic shift from OXPHOS to aerobic glycolysis that would otherwise favour cell migration and invasiveness." (PMID 30555683, 2018). "Whether MCU expression is connected with MYO10 or c-Met in breast cancer remains unraveled." (PMID 29137386, 2017). "To identify potential therapeutic agents targeting Breast Cancer (BRCA), we conducted a thorough analysis of drug responses and the effects of Mitochondrial Calcium Uniporter (MCU) knockdown using shRNA in BRCA cells." (PMID 38632642, 2024).
breast carcinoma (continued). "Other studies in breast cancer and neuroblastoma cells have also highlighted a SOCE defect when MCU was silenced, and the requirement for mitochondrial Ca2+ uptake to ensure IP3-induced STIM1 oligomerization in HeLa cells." (PMID 28495532, 2018). "In vitro studies performed by Tang and coworkers have reported that the mitochondrial Ca2+ uniporter (MCU) plays a critical role in SOCE and energy metabolism, which, in turn, are essential for breast cancer cell migration." (PMID 30558192, 2018). "Accordingly, we show here that a positive correlation of MCU expression with HIF1A and its regulated genes exists in human breast cancer samples, indicating that, in parallel with HIF‐1α, MCU represents a novel marker of cancer progression." (PMID 27138568, 2016). "For example, our and other groups have demonstrated that mitochondrial calcium uniporter (MCU), a key mediator of mitochondrial Ca2+ uptake, is upregulated in several cancer cell types, including CRC, breast cancer, hepatocellular carcinoma (HCC) and glioblastoma (GBM)." (PMID 34235078, 2021). "For instance, the upregulation of MCU has been identified in endoplasmic reticulum-negative and basal-like breast cancer." (PMID 33114428, 2020). "This decline of [Ca2+]m by MCU silencing results in caspase-independent cell death in breast cancer, regardless of cytosolic calcium concentration [Ca2+]i." (PMID 31163640, 2019). "On the other hand, it has been reported that MCU silencing did not affect SOCE in three different breast cancer cell lines, attributing cell migration defects to a decrease in ROS production and HIF1 signalling." (PMID 28495532, 2018). "Indeed, overexpression of MCU and downregulation of MICU1 have been related to poor prognosis of breast cancer patients, while over expression of MICU1 and/or MCUb were associated to better prognosis." (PMID 30011966, 2018). "When different breast cancer subtypes where compared, a higher expression of MCU was highlighted in estrogen receptor-negative patient samples, especially in basal-like breast cancers compared to luminal A and B subtypes." (PMID 28740830, 2017). "Hence, MCU activity is not limited to the regulation of TNBC cell migration, but it controls the invasion potential of malignant breast cancer cells." (PMID 27138568, 2016). "Indeed, multiple in vitro studies using triple negative breast cancer (TNBC) and other breast cancer cell models have shown that depletion of MCU led to a drastic cell migration decrease, independent of cell proliferation." (PMID 28495532, 2018). "Moreover, several previous studies demonstrated that MCU is highly expressed in estrogen receptor-negative and basal-like breast cancers, both of which have poor prognoses." (PMID 29137386, 2017). "Importantly, significant correlations of MCU expression with both HIF1A and its target genes were found, indicating that MCU‐dependent HIF1A transcription may also occur in human breast tumors and that MCU may represent a novel regulator of breast cancer progression." (PMID 27138568, 2016).